RNU6-1130P (RNA, U6 small nuclear 1130, pseudogene)
Gene: Small nuclear RNA gene on chromosome X (130,310,072 to 130,310,178, reverse strand). Ensembl gene ENSG00000202304.
Homologues: Orthologues: chimpanzee U6 (97% identical), macaque U6 (93% identical), rabbit U6 (87% identical), mouse Gm24754 (84% identical), pig U6 (78% identical), dog U6 (76% identical). Paralogues in human: RNU6-15P (89% identical), RNU6-17P (88% identical), RNU6-18P (88% identical), RNU6-7 (88% identical), RNU6-8 (88% identical), RNU6-1 (87% identical), RNU6-12P (87% identical), RNU6-13P (87% identical), RNU6-2 (87% identical), RNU6-31P (87% identical), RNU6-32P (87% identical), RNU6-39P (87% identical), and 1286 more.